CCAR1 (cell division cycle and apoptosis regulator 1)
Description:
Associates with components of the Mediator and p160 coactivator complexes that play a role as intermediaries transducing regulatory signals from upstream transcriptional activator proteins to basal transcription machinery at the core promoter. Recruited to endogenous nuclear receptor target genes in response to the appropriate hormone. May thus play an important role in transcriptional regulation (By similarity). May be involved in apoptosis signaling in the presence of the reinoid CD437. Apoptosis induction involves sequestration of 14-3-3 protein(s) and mediated altered expression of multiple cell cycle regulatory genes including MYC, CCNB1 and CDKN1A. Plays a role in cell cycle progression and/or cell proliferation. In association with CALCOCO1 enhances GATA1- and MED1-mediated transcriptional activation from the gamma-globin promoter during erythroid differentiation of K562 erythroleukemia cells. Can act as a both a coactivator and corepressor of AR-mediated transcription. Contributes to chromatin looping and AR transcription complex assembly by stabilizing AR-GATA2 association on chromatin and facilitating MED1 and RNA polymerase II recruitment to AR-binding sites. May play an important role in the growth and tumorigenesis of prostate cancer cells.
Synonyms: CARP-1; CARP1; uc.285+; FLJ10590
Tractability: PROTAC: UniProt records ubiquitination sites on it; ubiquitination databases record sites on it; its protein half-life has been measured.
Gene: Protein-coding gene on chromosome 10 (68,721,012 to 68,792,377, forward strand). Ensembl gene ENSG00000060339.
Subcellular location: Cytoplasm, perinuclear region
Subcellular location (Human Protein Atlas): Nucleoplasm; Golgi apparatus
Pathways (Reactome):
Metabolism of RNA: mRNA Polyadenylation; mRNA Splicing - Major Pathway
Disease: Dengue Virus-Host Interactions
Gene Ontology:
Molecular function: protein binding; RNA binding; RNA polymerase II cis-regulatory region sequence-specific DNA binding; transcription coactivator activity; transcription corepressor activity
Biological process: positive regulation of apoptotic process; positive regulation of cell migration; positive regulation of cell population proliferation; negative regulation of DNA-templated transcription; positive regulation of DNA-templated transcription; regulation of DNA-templated transcription
Cellular component: Golgi apparatus; nuclear envelope lumen; nucleoplasm; perinuclear region of cytoplasm
Genetic constraint (gnomAD): Loss-of-function variants: 47 observed, 92.04 expected, observed/expected ratio (o/e) 0.51, 90% interval 0.4 to 0.65. The upper end of that interval is the gene's LOEUF score, 0.65, which puts it in group 2 of 6, group 1 being the genes least tolerant of losing a copy. Missense variants: 641 observed, 912.06 expected, observed/expected ratio (o/e) 0.7, 90% interval 0.66 to 0.75. Synonymous variants: 287 observed, 320.65 expected, observed/expected ratio (o/e) 0.9, 90% interval 0.81 to 0.99.
Homologues: Orthologues: chimpanzee CCAR1 (99% identical), macaque CCAR1 (99% identical), dog CCAR1 (99% identical), rabbit CCAR1 (98% identical), pig CCAR1 (98% identical), guinea pig CCAR1 (98% identical), rat Ccar1 (95% identical), mouse Ccar1 (95% identical), tropical clawed frog ccar1 (79% identical), zebrafish ccar1 (71% identical), Caenorhabditis elegans ccar-1 (30% identical). Paralogues in human: CCAR2 (28% identical).
Diseases named in the same sentence as CCAR1 in open-access papers:
CCAR1 is named in the same sentence as 34 diseases in open-access papers, as found by Europe PMC text mining. Sharing a sentence is not in itself a finding about the gene and the disease. The quoted sentences say what the papers report.
breast carcinoma (11 papers, 2013 to 2025). "CCAR1 was initially identified as a perinuclear phosphoprotein that induces apoptosis in breast cancer cells during chemotherapy." (PMID 40130381, 2025). "In breast cancer, CCAR1 interacts with coactivators of estrogen receptor signaling to promote the proliferation of breast cancer cells 46,47." (PMID 39247813, 2024). "CCAR1 expression is reduced in poorly differentiated breast cancers and FADD expression is downregulated during thyroid adenocarcinoma progression, with both cancers showing aberrant PI3K/AKT/mTORC1 pathway activation." (PMID 31285545, 2020). "On the one hand, in breast cancer cells, CCAR1 is required for apoptosis induced by drugs such as CD437, Adriamycin, and Etoposide." (PMID 28230774, 2017). "CCAR1 is important for estrogen-induced expression of ERα target genes and estrogen-dependent growth of breast cancer cells." (PMID 23887938, 2013). "A positive correlation was recorded between STK33 and CCAR1 in basal‐like breast cancer." (PMID 40908551, 2025). "CCAR1 is an important activator for maintaining the growth of breast cancer." (PMID 37347215, 2023). "However, CCAR1 has also been shown to be essential for estrogen-induced gene expression and the estrogen-dependent growth of human breast cancer cells." (PMID 28230774, 2017). "The large majority (10/13) of these genes were reported to play a role in the regulation of estrogen and/or progesterone response in human breast cancer (NCOA7:; NCOA3:; USP22:; MED24:; CCAR1:; CRY2:; STAT5B:; PAGR1:; TAF1:; PHB2:)." (PMID 35996163, 2022). "On the other hand, CCAR1 is also involved in estrogen receptor signaling and promotes the growth of MCF-7 breast cancer cells in response to estradiol (E2) treatment." (PMID 28230774, 2017). "Deletion in breast cancer (DBC1), which shows significant homology to CCAR1, has been reported as an AR co-activator." (PMID 23887938, 2013). "Moreover, the results indicated that elevated expression of STK33 and CCAR1 correlated with poor survival in breast cancer, suggesting that the STK33‐CCAR1 axis is likely to be a robust biomarker for predicting the prognosis of TNBC." (PMID 40908551, 2025). "In addition, cycle and apoptosis regulator 1 (CCAR1) which is downregulated in breast cancers and FADD which exerts pro-apoptotic activity in breast cancer were shown to mediate Akt-induced senescence." (PMID 34298660, 2021). "Cell cycle and apoptosis regulator 1 (CCAR1/CARP-1) was initially identified as a protein that was required for apoptosis signaling by a retinoid (CD437), as well as the chemotherapeutics Adriamycin (ADR) and Etoposide in the human breast cancer cells." (PMID 28230774, 2017).
hepatocellular carcinoma (8 papers, 2020 to 2025). A malignant tumor that arises from hepatocytes. "For instance, in hepatocellular carcinoma (HCC), Cell Cycle and Apoptosis Regulator 1 (CCAR1) is overexpressed and associated with poor prognosis." (PMID 40130381, 2025). "CircRNA ZKSCAN1 interacts with FMRP to prevent the binding of FMRP with CCAR1 complex in hepatocellular carcinoma." (PMID 36800233, 2023). "Circular RNAs modulate CSCs of hepatocellular carcinoma by competing binding with FMRP against CCAR1." (PMID 34774083, 2021). "Elevated levels of CCAR1 protein expression were detected in hepatocellular carcinoma (HCC) cases, which might attribute to microvascular invasion, intrahepatic metastasis, higher disease stage, and early recurrence." (PMID 37917782, 2023).
gastric cancer (6 papers, 2017 to 2026). A primary or metastatic malignant neoplasm involving the stomach. "The study further revealed that excessive nuclear activity of CCAR1 in gastric cells is associated with gastric cancer." (PMID 40978202, 2025). "In gastric cancer, the interaction between CCAR1 and β-catenin can promote the proliferation and migration of gastric cancer cells." (PMID 39247813, 2024). "RNAi-mediated CCAR1 suppression leads to cell growth inhibition, elevated apoptosis, and reduced migration and invasion in gastric cancer." (PMID 37917782, 2023). "On the other hand, for gastric cancer, shRNA directed against CCAR1 co-activator of β-catenin reduced 75% of tumor volume and lowered the growth rate." (PMID 29861465, 2018). "Here, we show that CCAR1 is required for the survival of gastric cancer cells, and that the suppression of CCAR1 results in a decreased invasive character of gastric cancer cells." (PMID 28230774, 2017). "Here, we show that elevated CCAR1 nuclear expression correlates with the occurrence of gastric cancer." (PMID 28230774, 2017). "Here, we show that a component of the Wnt signaling pathway, CCAR1, plays a critical role in the tumorigenesis of gastric cancer." (PMID 28230774, 2017). "Our data demonstrates that CCAR1 contributes to carcinogenesis in gastric cancer and is required for the survival of gastric cancer cells." (PMID 28230774, 2017). "A study investigated the role of CCAR1 in several human cancers, including gastric cancer." (PMID 40978202, 2025). "Besides CCAR1, a coactivator of β-catenin is considered to have a vital role in the tumorigenesis and metastasis of gastric cancer." (PMID 29861465, 2018). "The results of all the assays indicate that CCAR1 is essential for the migration and invasion of gastric cancer cells, and CCAR1 may be more important in the initiation and progression of gastric cancer than in that of colon cancer." (PMID 28230774, 2017). "In this study, we knockdown the expression of CCAR1 in two gastric cancer cell lines using shRNA." (PMID 28230774, 2017). "Consequently, the expression of several β-catenin target genes decreases, including Axin2, Lgr5, Cd44, Birc5, and c-myc, indicating that CCAR1 functions in the same way in gastric cancer cells as it does in colon carcinoma cells." (PMID 28230774, 2017). "Considering that Wnt signaling supports the maintenance of stomach stem cells, we speculate that CCAR1 may play a major role in the tumorigenesis and metastasis of gastric cancer." (PMID 28230774, 2017). "To investigate whether the effect of suppressed CCAR1 on gastric cancer cells could be extended to in vivo conditions, we used a mouse xenograft model to examine the tumorigenic capabilities of cells in vivo." (PMID 28230774, 2017). "The altered expression of these target genes may reflect the physiological functions of CCAR1 in gastric cancer cells, which are to maintain stem cell characteristics and suppress apoptosis." (PMID 28230774, 2017). "Besides examining the effects of reduced-CCAR1 expression on the growth of gastric cancer cells, we also investigated CCAR1’s functions on other characteristics of gastric cancer cells." (PMID 28230774, 2017). "Besides regulating cell growth, CCAR1 also functions as a mediator of oncogenic transformation in gastric cancer cells." (PMID 28230774, 2017). "We further assessed the role of CCAR1 in the growth of gastric cancer cells." (PMID 28230774, 2017). "To investigate whether the expression of CCAR1 participates in the occurrence of gastric cancer, we analyzed the expression level of the CCAR1 protein by immunohistochemical (IHC) staining, on a tissue microarray (TMA) containing matched adjacent normal mucosa and gastric cancer tissue (n = 67)." (PMID 28230774, 2017). "Interestingly, Lgr5 and CD44 are two known stem cell markers, suggesting that CCAR1 may also be important for the maintenance of gastric cancer stem cells." (PMID 28230774, 2017).
gastric cancer (continued). "Since studies have shown that the deregulation of many Wnt signaling components contributes to the development of gastric cancer, it is of interest to investigate whether CCAR1, a key coactivator of β-catenin, plays a role in the neoplastic transformation of gastric cancer." (PMID 28230774, 2017). "Thus, based on our study, we speculate that CCAR1 may serve as a good therapeutic target for treating gastric cancer patients." (PMID 28230774, 2017). "Over the short 25.4-month median follow-up period, we observed that gastric cancer patients with moderate/strong CCAR1 expression had a poorer prognosis than those with negative/weak CCAR1 expression, but did not meet statistical significance." (PMID 28230774, 2017). "However, the function and clinical significance of CCAR1 in gastric cancer have not been elucidated." (PMID 28230774, 2017).
colorectal cancer (4 papers, 2017 to 2023). A primary or metastatic malignant neoplasm that affects the colon or rectum. "The same mechanism is utilized in 5-fluorouracil resistant colorectal cancer models as CCAR1 associates with β-catenin and triggers a stemness-like phenotype by inducing Myc among others." (PMID 37173882, 2023). "Moreover, depletion of CCAR1 lead to a significant reduction in the proliferation, migration and invasion phenotype in prostate, gastric and colorectal cancers." (PMID 30523220, 2018). "Previous studies have shown that CCAR1 is a novel component of Wnt/β-catenin signaling, that plays an important role in the transcriptional regulation by β-catenin and which is involved in the neoplastic transformation of human colorectal cancer cells." (PMID 28230774, 2017).
lung cancer (4 papers, 2018 to 2024). A malignant neoplasm involving the lung. "In lung cancer, CCAR1, as the target gene of miR-627-3p, affects the proliferation and invasion ability of lung cancer cells 48,49." (PMID 39247813, 2024). "SRSF5 has been shown to modulate apoptosis in lung cancer by controlling the alternative splicing of CCAR1." (PMID 37190199, 2023). "Our current findings suggest that SRSF5 promotes tumor growth largely dependent on the splicing of CCAR1, at least in lung cancer cells." (PMID 29942010, 2018). "SRSF5 regulates tumorigenesis of lung cancer cells through AS of CCAR1 pre-mRNA, and aberrant alternative splicing is a major contributor to cancer development." (PMID 29942010, 2018). "Together, these results indicate that SRSF5 is involved in human lung cancer development, probably through regulating alterative splicing of CCAR1 pre-mRNA." (PMID 29942010, 2018). "The increased acetylation of SRSF5 in human lung cancers is conducive to stabilization of SRSF5 and activation of AS of CCAR1, which further promotes the tumor growth." (PMID 29942010, 2018).
prostate carcinoma (4 papers, 2013 to 2024). A carcinoma that arises from epithelial cells of the prostate gland. "Given our findings that CCAR1 interacts with members of the NR family, such as ERα and glucocorticoid receptor (GR), we first examined the association between endogenous CCAR1 and AR in AR-positive LNCaP prostate cancer cells by coimmunoprecipitation (CoIP) assays." (PMID 23887938, 2013). "Furthermore, depletion of CCAR1 decreased the clonogenic survival of LNCaP cells and inhibited LNCaP cell migration and invasion, suggesting that CCAR1 is required for cellular properties associated with the transformed phenotype of prostate cancer cells." (PMID 23887938, 2013). "The apoptosis regulatory factor CCAR1 plays an important role in promoting cancer, and deletion of CCAR1 inhibits the occurrence and development of prostate cancer cells." (PMID 37347215, 2023). "In this study, we showed that CCAR1 is required for growth and tumorigenic properties of prostate cancer cells." (PMID 23887938, 2013). "Collectively, these results strongly suggest that CCAR1 plays a pivotal role in tumorigenic growth of prostate cancer cells." (PMID 23887938, 2013). "To investigate the possible role of CCAR1 in prostate cancer growth, we examined the effect of reduced CCAR1 levels on DHT-stimulated cell proliferation in LNCaP cells infected with lentiviruses expressing a shNS or CCAR1 shRNA." (PMID 23887938, 2013). "In these studies, expression of CCAR1 mRNA was higher in prostate carcinoma samples than in normal prostate gland samples, suggesting that CCAR1 might play an important role in the growth and tumorigenesis of prostate cancer cells." (PMID 23887938, 2013). "Furthermore, CCAR1 depletion inhibited the growth, migration, invasion of prostate cancer cells and reduced the tumorigenicity of prostate cancer cells in vivo." (PMID 23887938, 2013). "To further characterize the mechanism by which CCAR1 contributes to transcriptional activation by NRs, we explored the possibility that CCAR1 may play a role in AR-mediated transcription and contribute to the tumorigenic potential of prostate cancer cells." (PMID 23887938, 2013). "Our study thus suggests CCAR1 as a potential therapeutic target for prostate cancer." (PMID 23887938, 2013). "In this study, we show CCAR1 as a key factor in androgen signaling in prostate cancer cells." (PMID 23887938, 2013). "To examine whether CCAR1 is directly involved in AR-mediated transcription, we performed ChIP assays in prostate cancer cells." (PMID 23887938, 2013). "Furthermore, CCAR1 silencing reduced the migration, invasion, survival and tumorigenic potential of prostate cancer cells." (PMID 23887938, 2013). "Given that CCAR1 is required for optimal recruitment of MED1 to AR-binding sites, it will be interesting to test whether CCAR1 also contributes to UBE2C locus looping and castration-resistant prostate cancer progression." (PMID 23887938, 2013).
colon carcinoma (3 papers, 2015 to 2020). "Recently, a study revealed that CCAR1 associates with β-catenin and enhances the transcriptional activation of β-catenin target genes in colon cancer cells." (PMID 28230774, 2017). "Depletion of CARP-1/CCAR1 or β-catenin attenuated ability of the colon cancer cells to form colonies in soft agar." (PMID 25894788, 2015). "Another recent study revealed CARP-1/CCAR1 is a binding partner of β-catenin and enhances the transcriptional activation of β-catenin-Wnt target genes, and mediates anchorage independent growth of colon cancer cells." (PMID 25894788, 2015).
ovarian carcinoma (3 papers, 2020 to 2022). A malignant neoplasm originating from the surface ovarian epithelium. "Because ovarian cancer uniquely presents at a more advanced stage relative to other cancers, we ran a sensitivity analysis that excluded the cases of ovarian cancer; enrichment of low-stage cancers in the anti-CCAR1–positive group remained significant (P = 0.05, Fischer’s exact test)." (PMID 35040440, 2022). "Interestingly, CCAR1 gene expression levels have been demonstrated to associate with cancer survival, although results vary with cancer type; low CCAR1 expression levels correlate with increased survival in liver and renal cancers and the opposite has been shown in ovarian cancers." (PMID 35040442, 2022). "While cancer types were largely similar in the anti-CCAR1–positive versus anti-CCAR1–negative autoantibody groups, the anti-CCAR1–negative group had 3 ovarian cancers, whereas the anti-CCAR1–positive group had none." (PMID 35040440, 2022).
dermatomyositis (2 papers, 2022 to 2024). Dermatomyositis (DM) is a type of idiopathic inflammatory myopathy characterized by evocative skin lesions and symmetrical proximal muscle weakness. "In anti-TIF1γ positive dermatomyositis (DM) patients from the USA, anti-Sp4 and anti-CCAR1 autoantibody frequencies are reported as 32% and 43% in adults and 9% and 19% in juveniles, respectively." (PMID 39514366, 2024).
neuroblastoma (2 papers, 2014 to 2023). Neuroblastoma (NB) is the most common solid, extracranial childhood tumor. "TET1 rs3998860 and rs12781492 may increase neuroblastoma risk by influencing mRNA expression of CCAR1." (PMID 37347215, 2023).
renal carcinoma (2 papers, 2022). A carcinoma arising from the epithelium of the renal parenchyma or the renal pelvis. "Previous reports have identified increased expression of CCAR1 in liver and renal cancer, where high expression of CCAR1 correlates with poor overall survival." (PMID 36418423, 2022).
bladder cancer (1 paper, 2021). "Circular RNA circRIMS1 promotes malignant process by binding miR-433-3p and upregulating CCAR1 expression in bladder cancer." (PMID 34093821, 2021).